CD209 (CD209 molecule)
Diseases named in the same sentence as CD209 in open-access papers (continued):
Sharing a sentence is not in itself a finding about the gene and the disease.
tumor (129 papers, 2007 to 2025). "Results show that C3AR1 has the strongest correlation with M2 macrophages (CD163, MRC1, CD209), tumor-associated macrophages (CCL2, CD86, CD68) and monocyte immune markers, including (CD14, CD33, ITGAX)." (PMID 37005667, 2023). "Higher CD209+/CD83+ cell density ratio at the tumor margin was associated with higher risk of ADT and lethal PCa while higher density of CD163+ cells in the normal-like adjacent epithelium was associated with a higher risk of lethal PCa." (PMID 37435060, 2023). "Here, we demonstrated a profiling study on CD209 expression levels in both pan-cancer tissues and healthy tissues and the association of CD209 with infiltrating immune cells in tumor patients." (PMID 35783255, 2022). "CD14+ tumor-infiltrating cells expressed higher levels of PD-L1 and CD209 than circulating T cells, while a higher percentage of tumor-associated CD3+ T cells expressed PD-1." (PMID 34945784, 2021). "A correlation of immune cell marker genes, including tumor-associated macrophages (TAMs) (CD209, CD206/MRC1, IL6, IL8, and CXCL10), MDSCs (CD33 and IL6), dendritic cells (DCs) (CD11c/ITGAX, CD209, TNF, and CD80) and Fusobacterium has been found in humans." (PMID 33823861, 2021). "Indeed, a higher infiltration of CD163+ M2 macrophages in the normal adjacent epithelium as well as a higher infiltration of CD209+ immature DC at the tumor margin were associated with lethal PCa and BCR, respectively." (PMID 38887294, 2024). "The gene markers of M1 macrophages, such as PTGS2 and NOS2, had weak correlations with CD209 expression, whereas M2 macrophage markers had moderate and strong correlations, revealing the potential regulatory role of CD209 in tumor-associated macrophage (TAM) polarization." (PMID 35783255, 2022). "Interestingly, in NET G1/G2 and NET G3/NEC we also observed higher expression of CD209/DC-SIGN, a marker for dendritic cells but also for tumor-associated macrophages (TAMs) and immature immunosuppressive myeloid cells." (PMID 33228231, 2020). "Moreover, we have previously found an association between CD209+ tumour-associated macrophages (TAM) and an ongoing T cell response in a tumoural setting." (PMID 30510965, 2018). "Additionally, CD209, an important immune receptor, shows a significant positive correlation with resting mast cells (R = 0.78, p = 0.013), suggesting its potential involvement in tumour‐associated inflammatory responses." (PMID 40682474, 2025). "To elucidate the mechanism behind the superior tumor control observed in the RT and SIRPα blockade combination, we used flow cytometry to measure SIRPα, CD209, and HLA-DR expression in tumor tissues from the xenograft models." (PMID 40208335, 2025). "We assessed the expression of surface markers characteristic of both pro-inflammatory (CD86) and anti-inflammatory (CD163, CD206, CD209) phenotypes on macrophages cultured either in monocultures or in co-culture with tumor cells." (PMID 41009763, 2025). "Further, we found that SLC7A8 + macrophages highly expressed CD163 and CD209 and other marker genes of M2 macrophages, which played a role in promoting tumor, inhibiting immune response, inducing angiogenesis and tissue repair." (PMID 38582791, 2024). "The immunophenotypic characterization verified the presence of a CD163+CD209+ double-positive TAM population from the tumor." (PMID 39498357, 2024). "A distinct overexpression of CD1c, CD2, CD3, CD4, CD11c, CD14, CD20, CD44, CD56, CD105, CD146, and CD209 was identified in LCa patients compared to healthy controls, correlating positively with tumor presence." (PMID 38902710, 2024). "CD209 as representative M2 marker was upregulated in coculture with all three tumor cell lines and in triple culture with HDFs." (PMID 37947617, 2023). "We have previously shown that CD209+ cell numbers were higher in advanced ccRCC tumors with poor prognostic tumor stage." (PMID 36291154, 2022).
tumor (continued). "CD209 exhibits high transcript levels in pN+ macrophages that can potentially prevent CD8+ T cells from exerting their full cytotoxicity against tumor cells." (PMID 36344512, 2022). "CD209 (DC-SIGN), MARCO, and RELN genes function in the downregulation of the immune system through IL10 and inhibitory tumor-associated macrophage mechanisms, respectively." (PMID 34349241, 2022). "The CD209 expression showed significant positive correlations with tumor purity and infiltrating levels of immune cells in LUSC patients." (PMID 35783255, 2022). "DCs interspersed within MF cells were mostly at an immature state (CD209/DC-SIGN1 DCs) and in close contact with tumor cells." (PMID 34685762, 2021). "Dioscin treatment (30 mg/kg and 60 mg/kg) decreased the population of F4/80+CD209+ macrophages that infiltrated tumour cells (5.03 ± 0.62% and 5.66 ± 0.37% vs 7.71 ± 0.61%, respectively, both P < 0.05)." (PMID 32618105, 2020). "Further studies aimed at defining the role played by CD209+ macrophages in these tumours are warranted." (PMID 30510965, 2018). "The finding that co-localization of CD209 and p-ERK1/2 in LLC tumor tissue demonstrated that ERK of CD209+ macrophages was relatively active comparing to tumor cells." (PMID 25313135, 2014). "On the other hand, immunofluorescence derived from LLC tumor tissue showed CD209 colocalized with p-ERK1/2, and the infiltration of CD209+ macrophages was increased as well as the expression of p-ERK1/2 in hypoxia-acclimated animals." (PMID 25313135, 2014). "Additionally, CD209's specific correlations with various immune cells suggest its potential role in modulating tumour immune responses." (PMID 40682474, 2025). "Moreover, we found increased M2 macrophage infiltration and decreased expression of Cd209 in the tumor microenvironment of MAG and DOX combinatorial therapy treated tumors." (PMID 38992659, 2024). "In addition, the correlation between the CD209 expression and the marker genes of immune cells indicated the critical role of CD209 in the regulation of tumor immunology in LUSC patients." (PMID 35783255, 2022). "Since CD209 is a potential specific receptor for SARS-CoV-2, these findings can provide a therapeutic clue for tumor patients and may prevent the risk of COVID-19 infection." (PMID 35783255, 2022). "We designated this myeloid subpopulation “enriched-in-renal-carcinoma DCs” (ercDCs), due to its strong enrichment in the tumor center, where they represent over 60% of the CD209+ population (mean, 62%; range, 26% to 80%), compared to non-tumor kidney cortex (mean, 19%; range, 0% to 43%)." (PMID 36291154, 2022). "CD209+ DCs, in particular, may play a role in promoting tumor progression by decreasing the recruitment of Th1 T cells into the tumor." (PMID 34831452, 2021). "Indeed, DCs acquire an immunosuppressive phenotype (CD14+/CD16+/CD68+/CD124+/CD209+; PD-L1 overexpression), becoming incapable of cross-presenting tumor antigens to T cells and inhibiting the T cell response." (PMID 34945784, 2021). "Interestingly, FOLR2, CD163, LILRB5, CD209 and C1QC were identified as genes of the “anti-inflammatory gene set”, whose expression is also seen in tissue-resident macrophages and tumor-associated macrophages." (PMID 32532019, 2020). "Of interest, most of these M2 macrophages (CD209+) were situated at hypoxic regions (PIMO+), indicating tumor hypoxia might be highly associated with the M2 polarization of macrophages." (PMID 25313135, 2014). "Additionally, tumor glycoproteins have been identified as binding partners for CD209." (PMID 38593053, 2024). "In this study, we demonstrated that CD209 (DC-SIGN) was abundantly expressed in many types of immune cells, especially in monocytes and myeloid DCs, which might contribute to the weakened immune response in elderly tumor patients." (PMID 35783255, 2022).
tumor (continued). "Interestingly, we found that the CD209 expression level was positively associated with the immune markers of tumor-associated macrophages (TAMs) and M2 macrophages but not M1 macrophages." (PMID 35783255, 2022). "In addition, an up-regulation of macrophage receptors involved in cell activation and recruitment (e.g. CD80, CD86, CSF3R, CSF2RB and CD209) was observed 8 hours after treatment possibly indicating an increased presence of activated macrophages in the tumor at this point in time." (PMID 27463372, 2016). "By reducing the expression of M2 macrophage markers (CD163 and CD209) and suppressing the release of tumor-promoting factors such as MMP-9, RANTES, and VEGF, Deoxyschizandrin mitigates the supportive role of TAMs in tumor progression." (PMID 40330466, 2025). "In TAMs, phlorotannins reduced the expression of M2-like markers (CD163 and CD209) and decreased the secretion of IL-10, IL-17, and VEGF, all of which collectively support tumor progression." (PMID 41590709, 2025). "The combination of RT and anti-SIRPα showed superior tumor control compared to anti-PD1, which is potentially due to the enhanced antigen presentation capacity of SIRPα + CD209 + cells." (PMID 40208335, 2025). "They found significant infiltration of CTCL lesions by immature CD209/DC-SIGN+ DCs, which were in close contact with tumor cells." (PMID 40427608, 2025). "Tumor-promoting genes such as CD163 and CD209 were highly expressed in the myeloid cells, and depletion marker genes such as TIGIT, LAG3 were highly expressed in NK/T cells." (PMID 38582791, 2024). "At the study evaluation timepoint of 2 h post H-FIRE, we observed differential gene expression changes in the genes IDO1, IL6, TNF, CD209, and FOXP3 in treated tumor regions relative to paired untreated tumor regions." (PMID 39335552, 2024). "Differential gene expression results revealed five genes (IDO1, IL6, TNF, CD209, and FOXP3) that were, on average, upregulated ≥ 2-fold or downregulated ≤ –2-fold in treated tumor regions relative to untreated tumor regions." (PMID 39335552, 2024). "Positive immune cells were observed in all areas but in different proportion for certain types of cells as for example CD209+ immature DC and CD163+ M2-type MΦ were more abundant at the tumor margin." (PMID 37435060, 2023). "A relationship between the ercDC from RCC tumor tissue and myeloid cells from chronic inflammatory kidney pathologies was previously suggested based on the triple marker staining of CD14, CD209 and CD163." (PMID 36291154, 2022). "Significant suppression of CD163 and CD209 expression and suppression of mRNA expression with subsequent reduction in MMP-9, RANTES, VEGF production (tumor growth factors secreted by macrophages)." (PMID 36140188, 2022). "This study will shed light on the therapeutic potency of CD209 antigens and help prevent or attenuate SARS-CoV-2 infection in specific tumor patients." (PMID 35783255, 2022). "IHC staining was performed to examine CD209 and HAVCR2 protein levels in GC tissues and corresponding non-tumor tissues." (PMID 36106123, 2022). "A recent survey of tumor tissues from patients with GBM correlated the infiltrative character of GBM malignant cells with an increased expression of CCL15, CCL17, CD209, and TNF-α genes." (PMID 35992881, 2022). "The IHC results showed that the average expression score of CD209 and HAVCR2 was significantly higher in epithelial tissues of GC than in adjacent non-tumor counterparts." (PMID 36106123, 2022). "TNC and CD209 genes play an important role in the progression of GBM by regulating the migration, adhesion, and invasion of tumor cells into adjacent tissues." (PMID 35992881, 2022). "We then examined the changes in M2-like TAM markers (CD163, CD206, CD209, IL-10 and Arginase 1) and M1-like TAM markers (CD80, CD86, IL-12, and TNFα) induced by CM from ILT4-downregulated tumor cells." (PMID 33537094, 2021).
tumor (continued). "In contrast, the CD209+ CD83− NTLS-DC subpopulation has an immunosuppressive phenotype and develops under the stimulation of various tumor-derived factors, including IL-10, TGF-β, prostaglandin E2 (PGE2), and chemokines." (PMID 33746989, 2021). "IF and confocal analysis confirmed the coexpression of the CD209 myeloid marker and the cytokeratin CAM5.2 tumour marker." (PMID 30510965, 2018). "These in vitro findings demonstrate that SIRPα + CD209 + cells are radioresistant and exhibit significant upregulation of HLA-DR, independent of the presence of tumor cells, following radiation exposure." (PMID 40208335, 2025). "Normal mammary fat pads (MFPs) and tumor sections (n = 5 per group) were double-stained for Lyve-1 to identify single M-LECP cells and eight proteins known to promote cell fusion including CD36, CD98, CD209, Dap12, Dc-stamp, Sirp-a, Sirp-b1, and stabilin-1." (PMID 40507286, 2025). "In addition, glycosylated tumor antigens such as CEA and MUC1 on CRC cells have been shown to serve as ligands for DC-SIGN (CD209) on DCs." (PMID 41320679, 2025). "Single-cell expression analysis revealed that KRT5 and FABP7 were highly enriched in tumor cells, UGT2B4 was predominantly expressed in epithelial cells, BIRC3 and KLRB1 were enriched in CD8+ T cells, while MRC1 and CD209 were highly expressed in monocytes/macrophages." (PMID 40612672, 2025). "moDC were CD209+ and HLA-DR, DP, DQ+ before co-culture with transfected tumor cells and levels were not affected upon co-culture." (PMID 39007281, 2024). "Post-treatment, the tumor microenvironment showed immunomodulatory changes, including altered macrophage infiltration and significant gene expression changes related to inflammation and immune response, such as IDO1, IL-6, TNF, CD209, and FOXP3." (PMID 39765586, 2024). "CD209+ and CD163+ cells were more abundant at the tumor margin." (PMID 37435060, 2023). "Similarly, CAFs express neuropilin-1 (NRP1) and integrins; TAMs may express DC-SIGN and ACE2; endothelial cells lining tumor vasculature express ACE2, NRP1, and integrins; and APCs like DCs express DC-SIGN (CD209) and L-SIGN, collectively enhancing OV tropism and entry." (PMID 40927720, 2025). "In view of the profiles of CD209 expression and their correlation with proinflammatory chemokines and cytokines and various immune cells in LUSC patients, CD209 may have great potential in exacerbating the “cytokine storm” in SARS-CoV-2-infected specific tumor patients." (PMID 35783255, 2022). "Expression of CD163, CD209 and CD86 markers was not affected by the presence of tumor cells or by chemotherapeutic treatments, doxorubicin or epirubicin." (PMID 41009763, 2025). "IHC analysis showed that these areas were positive for CD209, CD14, and the tumour marker WT1, whereas they were negative for the lineage-specific marker CD45 (data not shown)." (PMID 30510965, 2018). "Thus the increase of CD209+ macrophages in hypoxia-acclimated animals might mainly result from the effect of hypoxia on macrophage polarization rather than the infiltration of macrophages into tumor tissues." (PMID 25313135, 2014).
cancer (57 papers, 2007 to 2026). A tumor composed of atypical neoplastic, often pleomorphic cells that invade other tissues. "We probed the underlying therapeutic implications of CD209 in SARS-CoV-2 infections in carcinoma patients." (PMID 35783255, 2022). "Among the dendritic cell subset markers of the monocyte-derived dendritic cells, it is noteworthy that CD1A mRNA counts were also found to be associated with the risk of relapse and cancer progression, while CD209 was associated only with an increase in SPP1 levels." (PMID 38275392, 2023). "CD209 binds Lewis antigens highly expressed in cancers, facilitating T-cell priming and initiating immune cascades." (PMID 39108264, 2024). "Further validation of animal experiments and clinical trials is required to evaluate the effect of anti-CD209 therapy in specific cancer patients with SARS-CoV-2 infection." (PMID 35783255, 2022). "Taken together, CD209 plays critical roles in both immunology and metabolism in various cancer types." (PMID 35783255, 2022). "We also found that CD209 expression was correlated with diverse immune infiltration levels in various cancer types." (PMID 35783255, 2022). "The efficiency of CD209 in the survival of pan-cancer patients was further explored with the Kaplan–Meier plotter (Győrffy, 2021)." (PMID 35783255, 2022). "In this study, we first comprehensively investigated the expression profiles of CD209 in malignancies in both pan-carcinomas and healthy tissues based on bioinformatic techniques." (PMID 35783255, 2022). "Besides, more DC-targeted cancer antigen vaccines, such as CD209/DC-SIGN-fusion protein, are still under evaluation." (PMID 38008741, 2023). "The CD209 expression declined dramatically in various cancer types infected by SARS-CoV-2." (PMID 35783255, 2022). "CD209 antigen (D-mannose) might exhibit beneficial therapeutic effects on SARS-CoV-2 treatment together with other effective strategies in specific cancer patients." (PMID 35783255, 2022). "Therefore, we first investigated whether CD209 expression was correlated with TIIC levels in various cancer types from TIMER." (PMID 35783255, 2022). "The results showed that the CD209 expression was evidently correlated with the infiltration of CD8+ T cells, CD4+ T cells, Treg cells, B cells, monocytes, NK cells, myeloid dendritic cells, neutrophils, macrophages, and cancer-associated fibroblasts in pan-carcinoma patients." (PMID 35783255, 2022). "Furthermore, the CD209 expression is closely related to prognosis in some specific cancer types." (PMID 35783255, 2022). "The efficient uptake of MP by M2 macrophages accompanied by increase production of CCL22 and CD209, which recruit regulatory T cells and dendritic cells into cancer tissue, enhanced the M2 immune activity and can be used to target macrophages involved in cancer progression." (PMID 33790914, 2021). "Consistently, immunostaining using CD80, a marker specific for M1, and CD209, a marker specific for M2a, showed that the various macrophages retained the expression of their respective markers after 36 h, even within the 3D collagen matrix in the presence of carcinoma aggregates and HUVECs." (PMID 26231039, 2015). "In the current study, cancer cell-conditioned medium and IL-10 induced higher expression levels of CD14, CD16 and CD163 with normal DC markers, including CD11c and CD209." (PMID 25013476, 2014). "Of note, comparing with cancer cells, the activation of ERK1/2 was predominately observed in CD209+ macrophages." (PMID 25313135, 2014). "Mature MDDC from healthy donors and cancer patients up-regulated the expression of CD83, CD86, frequencies of IL-12+ and COX-2+ cells, and secretion of IL-8; and down-regulated CD209 expression relative to their immature counterparts." (PMID 17477875, 2007). "Pharmacological inhibition of CD209 antigen (D-mannose), together with other anti-SARS-CoV-2 strategies, might provide beneficial therapeutic effects in specific cancer patients." (PMID 35783255, 2022).
cancer (continued). "The higher expression of CD209 triggers an immune response and may subsequently lead to a severe response to SARS-CoV-2 infection in cancer patients." (PMID 35783255, 2022). "Thus, we estimated the landscape profile of CD209, a potential SARS-CoV-2 receptor, in pan-carcinoma patients." (PMID 35783255, 2022). "In summary, these results revealed that CD209 was specifically correlated with immune infiltrating cells in specific tumors, which might ultimately contribute to the immune storm in SARS-CoV-2-infected cancer patients." (PMID 35783255, 2022). "The number of CD209+ MDDC from cryopreserved PBMC of healthy donors was higher, although not significantly, when compared to that of cancer patients (data not shown)." (PMID 17477875, 2007).